BCL2 (BCL2 apoptosis regulator)
Diseases named in the same sentence as BCL2 in open-access papers (continued):
Sharing a sentence is not in itself a finding about the gene and the disease.
cancer (continued). "Due to their key role in the pathogenesis of cancer through the regulation of apoptosis, the B-cell leukemia/lymphoma-2 (BCL-2) family proteins have been an attractive target for cancer therapy for the past decades." (PMID 36639602, 2023). "The DOX and Bcl‐2‐siRNA can be conjugated to CS‐modified polymeric nanoparticles and then, synergistic cancer therapy is provided." (PMID 36684100, 2023). "EVs engineered to contain miR-205 caused a greater number of cancer cells to be in apoptosis and fewer cancer cells to be viable through the decreased expression of an anti-apoptotic gene Bcl-2." (PMID 37894887, 2023). "Bcl-2 can bind onto Bax, and this enables the survival of cancer cells by inhibiting cell apoptosis." (PMID 36829996, 2023). "This peptide pool contained proteins involved in cancer development and migration, such as Fascin, Ape-1, Bcl-2, and VCP." (PMID 36679991, 2023). "The toxic effect on cancer cells arises via inhibition of telomerase activity due to interaction with c-Myc, hTel, and Bcl-2 G4-DNA." (PMID 36456886, 2023). "In support, MSCs inhibit Bcl2, β‐catenin, and Wnt signaling, trigger apoptosis in cancer cells (Y.-H." (PMID 36561333, 2023). "On the other hand, the expression level of the anti-apoptotic gene Bcl-2 was decreased significantly in both cancer cell lines after treatment with BHE." (PMID 37464362, 2023). "Quercetin has been shown to promote apoptosis of cancer cells by regulating the NF-κB factor and Bcl-2 and Bax genes." (PMID 37569275, 2023). "In the current network, BCL2, a hub node and an important targeted point for cancer therapy, was downregulated by 3 genera, including Eubacterium, Bifidobacterium, and Bacteroides." (PMID 38035339, 2023). "Because of its role in regulating apoptosis through binding, this hydrophobic groove on pro-survival BCL-2 proteins is an attractive target for anti-cancer drugs that can counteract the overexpression of the pro-survival BCL-2 proteins." (PMID 36795726, 2023). "In our present study, we found that silencing of NONO induced the loss of mitochondrial membrane potential (ΔΨm) and increased the Bax/Bcl2 ratio that correlates with the sensitivity of cancer cells to chemotherapy drugs." (PMID 37370134, 2023). "These compounds have shown efficacy in pre-clinical studies, and some have entered clinical trials for cancer therapy, with the BCL-2 specific inhibitor venetoclax FDA approved for the treatment of patients with CLL or AML." (PMID 36342579, 2023). "Apoptotic genes such as the FLICE inhibitory protein, survivin, XIAP, the c-IAP1/2 inhibitor, and the Bcl-2 group of proteins are overexpressed in many types of cancer cells, and the NF-κB factor is responsible for inducing these genes." (PMID 37569275, 2023). "BCL-2 protein has numerous roles in cellular pathways that are related to cell death or cell survival as well as act as important factors in resistance to cancer therapeutics." (PMID 37232720, 2023). "The development of new Bcl-2 inhibitors represents a promising therapeutic approach in oncology, with the potential to overcome drug resistance and improve the efficacy of cancer treatments." (PMID 37834104, 2023). "For instance, the anti-apoptotic BCL-2 members are often overexpressed in cancers, leading to the impaired apoptotic pathway and chemoresistance." (PMID 36755067, 2023).
cancer (continued). "Hesperidin treatment inhibited Bcl-2 mRNA expression in cancer cells, and this expression fell as the concentration of hesperidin gradually increased." (PMID 37446814, 2023). "STAT3 is regarded as a therapeutic target in many cancers and regulates cyclinD1, c-Myc, Bcl-2, survivin and ICAM-1, related to cell proliferation, survival, migration, invasion, stemness, immunosuppression and angiogenesis." (PMID 37147297, 2023). "Gene therapy using siRNA to downregulate the expression of Bcl-2 represents a promising tool in cancer treatment." (PMID 37233460, 2023). "The previously discussed anti-apoptotic gene products, Bcl-2, Bcl-xL, Mcl-1 and survivin, have been found to be overexpressed in several human cancers." (PMID 37686541, 2023). "Antiapoptotic B-cell lymphoma-2 (BCL-2) family members are core regulators of the apoptotic process, rescue cancer cells from apoptosis, and confer prosurvival properties to tumors." (PMID 37894324, 2023). "The BCL-2 proteins are recognized for their regulatory effect in programmed cell death, and they are frequently dysregulated in cancer, as well as in diverse autoimmune and degenerative diseases." (PMID 36980256, 2023). "It has been widely proposed that Bcl‐2 expression in cancer patient samples can promote cell migration, invasion, and metastasis by inducing MMP9 protein expression in various tumors." (PMID 35702822, 2023). "The elevated level of Bcl-2 proteins is liable for the cancer induction in cells; therefore, inhibition of Bcl-2 is vital to suppress cancer." (PMID 37204562, 2023). "Gossypol acetic acid, a polyphenolic compound isolated form cottonseeds, has been reported to inhibit Bcl-2, Bcl-xL and Mcl-1 function and have antiproliferative effects on some cancer cells in vitro." (PMID 37112871, 2023). "It has also been shown that these pro-apoptotic and anti-apoptotic BCL-2 families are regulated by survival signaling mechanisms and affect paclitaxel resistance in various cancer types." (PMID 38137377, 2023). "Recent intensive studies of BAX/BAK shuttling, BCL-2 protein interactions and active BAX complexes have laid the foundation for developing novel strategies for cancer therapy and analyzing cellular susceptibility to apoptosis." (PMID 37728427, 2023). "Cancer cells with a high level of Bcl2 have unbalanced apoptotic regulators and are addicted to Bcl2." (PMID 37496993, 2023). "On the other hand, non-pump resistance is driven by the overexpression of antiapoptotic proteins (e.g., B cell lymphoma 2 [Bcl-2]) that prevent apoptosis in cancer cells." (PMID 37242674, 2023). "Targeting Bcl-2 holds promise as a potential therapeutic approach for cancer treatment, with one peptide having been approved for treatment." (PMID 37240331, 2023). "SNPs related to Bcl-2/Bax gene promoters have been investigated in several studies on cancer initiation, development and progression." (PMID 37232720, 2023). "The Bcl-2 gene is upregulated in a wide variety of cancers including RCC and selective Bcl-2 inhibition was reported as a potential strategy in the treatment of RCC." (PMID 36440963, 2023). "The benefits of Pd (II) treatment were magnified by their ability to down-regulate the expression of Bcl2 proteins, which guided cancer cells toward apoptotic pathways." (PMID 38139837, 2023). "The relative ratio between pro-apoptotic and anti-apoptotic proteins determined by the division of means for Bax expression to Bcl-2 expression levels (Bax/Bcl-2 ratio) is more informative and has been regarded as a prognostic marker in various cancers." (PMID 36613399, 2023). "The results showed that the cancer control group (B) exhibited notably lower immunostaining intensity for Bax expressions and significantly higher staining intensity for Bcl-2 protein." (PMID 36826002, 2023).
cancer (continued). "The Bax/Bcl-2 quantity expression ratio in P4 was significantly (p < 0.05) upregulated in proliferating cancer cells, but in P4- and M2.1-differentiated cells these values were downregulated (p < 0.05)." (PMID 36613399, 2023). "Combined application of indirubin‐3‐monoxime and TQ on A549 cancer cells did increase apoptosis markers and also reduced the Bcl‐2/Bax ratio, inhibiting migration and metastasis of the cancer cells." (PMID 37697969, 2023). "The results showed that 6-gingerol therapy decreased the overexpression of NFk, AKT, and Bcl-2 genes in cancer cells." (PMID 36937441, 2023). "ABT-199/venetoclax is a selective and the first FDA-approved BH3 mimetic binding to the BH3 binding groove of BCL-2 with high affinity and being described to be active in numerous cancer types." (PMID 37210688, 2023). "The search for molecular substances that directly target members of the Bcl-2 family, including the Bcl-2 gene itself, is leading to new cancer treatments (Kelly and strasser, 2011)." (PMID 37324453, 2023). "Cancer cells evade apoptosis by upregulating Bcl-2 anti-apoptotic proteins or downregulating pro-apoptotic proteins." (PMID 37107299, 2023). "Abnormally high expression of pro-survival BCL-2 proteins is correlated with the development and poor prognosis of various cancers." (PMID 36342579, 2023). "Both Bax and Bcl-2 as well as their ratio have been regarded as prognostic markers in various types of cancers." (PMID 38003971, 2023). "In vitro experiments demonstrated significant downregulation of Bcl-2 mRNA levels and enhanced cell death compared to free drugs in multiple cancer cell lines." (PMID 37275244, 2023). "These BH3-based Bcl-2 inhibitors are a new class of cancer drugs that have been evaluated in pre-clinical and clinical trials." (PMID 37237269, 2023). "Taken together, apoptosis induction and cell proliferation inhibition via PI3K/AKT/mTOR and Bax/Bcl-2/Caspase-3 pathway are promising evidence to support B. coagulans MZY531 as a potential therapeutic agent for cancer." (PMID 37705007, 2023). "In malignant tumors, elevated levels of BCL-2 can be driven by various mechanisms, such as chromosomal translocations, gene amplification, and the downregulation or deletion of microRNAs involved in degrading BCL-2 RNA." (PMID 38026941, 2023). "Navitoclax is a senolytic agent that promotes the elimination of senescent cells in cancer and degenerative diseases by targeting prosurvival members of the Bcl2 gene family and is active in senescent embryonic fibroblasts." (PMID 38071330, 2023). "Cancer cells can survive by upregulating the anti-apoptotic BCL2 protein and downregulating the pro-apoptotic Bax protein." (PMID 38041055, 2023). "Myeloid cell leukemia 1 (Mcl‐1), a prosurvival Bcl‐2 protein, is commonly overexpressed in cancers that affect humans." (PMID 37970406, 2023). "NF-κB signaling can increase cancer cell-intrinsic expression of critical antiapoptotic mediators, including Bcl-xL, Bcl2, cFLIP, cIAP2 and Gadd45β by promoting tumor growth and protecting cancer cells from apoptosis-inducing chemotherapeutic agents." (PMID 36768145, 2023). "Among the cancer-associated proteins whose expression is downregulated by small molecule BRD4 inhibitors are the oncogenic driver c-Myc, the anti-apoptotic Bcl2, and cell cycle regulators such as the cyclin-dependent kinases." (PMID 36768967, 2023).
cancer (continued). "In this study, it was also observed that the metabolite modulates the expression of the Bax and Bcl-2 proteins, as well as the molecular chaperone HSP70, associated with oncogenesis in cancer cells where its expression is abnormally high." (PMID 37512512, 2023). "It is generally accepted that cancer drugs can target particular molecular proteins to inhibit the malignant behavior of cancer cells, such as BCL2." (PMID 36750914, 2023). "Tumor suppressor miRNA, miR34a, is believed to be frequently depleted in cancer tissues and it is associated with the genetic expression of multiple signaling pathways, including NOTCH-1, CD44, Bcl-2, Myc, Met, CDK-4/6, and various other biological molecules." (PMID 37149609, 2023). "BH3 mimetics are a type of anti-cancer drug that mimic the binding of BH3 domain protein to the hydrophobic groove of pro-survival BCL-2 proteins." (PMID 36795726, 2023). "As JNK separates Beclin-1, it relieves the inhibitory effect of Bcl-2, which is responsible for dictating macroautophagy in cancer-infected cells." (PMID 37893079, 2023). "Cancer cells inhibit the mitochondrial apoptosis pathway by upregulation of pro-survival BCL-2 proteins, which results in bound BAX and BAK proteins and inhibition of cellular apoptosis." (PMID 36795726, 2023). "In both cancer and senescence, overexpression of Bcl-2 counteracts the proapoptotic genes Puma and Noxa, thereby limiting apoptosis." (PMID 37047342, 2023). "Through the local stabilisation of the structure of these loops by CV, the gene expression of BCL2 in cancer cells was successfully repressed." (PMID 37658102, 2023). "Bcl-2 is a proto-oncogene, the expression product of which is suspected as the motivator for cancers and autoimmune diseases by activating superfluous cells." (PMID 37021044, 2023). "In cancer cells, Bcl-2 is often overexpressed, allowing the cells to evade apoptosis and continue to proliferate." (PMID 37185746, 2023). "High Nrf2 activity in cancer cells leads to the upregulation of various proteins associated with cancer progression, including ABCG2, VEGF, HO-1, Bcl-2, p62, and MDM2." (PMID 37759607, 2023). "Some cancer types exhibited significant up-regulation of pro-apoptotic proteins and down-regulation of the anti-apoptotic marker BCL2 following CHCP treatment." (PMID 37509349, 2023). "When cancer cells over-express pro-survival BCL-2 proteins, a potential remedy is the sequestration of these pro-survival proteins through a class of anti-cancer drugs called BH3 mimetics that bind in the hydrophobic groove of pro-survival BCL-2 proteins." (PMID 36795726, 2023). "Cancer cells evade apoptosis by increasing levels of anti-apoptotic Bcl-2 proteins including Mcl-16,7." (PMID 37481672, 2023). "After the treatments, the apoptotic counts were effectively increased and formononetin treatment contributed to the decrease in Bcl-2 protein level and the increase in Bax expression in cancer cells, which improved the Bax/Bcl-2 ratio." (PMID 37298670, 2023). "Despite BCL-2 levels being enhanced in parental cancer cells and macrophages, the induction was again more pronounced in putative THCs." (PMID 37848444, 2023). "Cancer cells often require high activity of antiapoptotic Bcl-2 proteins for cell survival and inhibition of apoptosis." (PMID 36902392, 2023).
cancer (continued). "Cancer cells traditionally upregulate BCL-2 anti-apoptotic proteins which provide them with resilience against stimuli, such as growth factor deprivation, hypoxia, and oxidative stress, that typically induce apoptosis in cells." (PMID 39872303, 2023). "Due to their known regulatory effects on cell death, anti-apoptotic members Bcl-2, Bcl-xL and Mcl-1 are of importance in cancer therapy as they prevent cell termination in cancer cells and promote the survival of these cancer cells." (PMID 37686541, 2023). "Obatoclax was developed as a pan-BH3 mimetic to induce apoptosis of cancer cells by disrupting multiple interactions, including those between anti-apoptotic BCL2 family proteins (BCL2, BCLXL, and MCL1) and BAX and BAK interactions." (PMID 37759469, 2023). "Simultaneously, the extracts downregulated the expressions of 5-LOX, Bcl2, and Bcl-xL, crucial in curbing cancer progression." (PMID 37894369, 2023). "Proteins of the B-cell lymphoma 2 (Bcl-2) family play a role in the regulation of apoptosis and confer resistance to traditional cytotoxic chemotherapy and monoclonal antibodies, making Bcl-2 an attractive target for therapeutic intervention in cancers." (PMID 36918935, 2023). "They found that reducing the Bcl-2 gene expression was the main anti-cancer mechanism of zingiberensis." (PMID 36984763, 2023). "The overexpression of Bcl-2 is seen in some cancer types and has a vital role in cancer development; therefore, silencing this gene is essential for cancer treatment." (PMID 37038689, 2023). "One mechanism for this evasion is the overexpression of prosurvival B-cell lymphoma-2 (BCL-2) family proteins, which gives cancer cells a survival advantage." (PMID 37601693, 2023). "The most significant synergism was found for navitoclax, which acts as a pro‐apoptotic anti‐cancer drug by inhibiting the anti‐apoptotic proteins Bcl‐2 and Bcl‐XL." (PMID 36781298, 2023). "Thapsigargin treated-cancer cells also increased the ER stress-induced apoptotic marker protein levels and Bax/Bcl2 ratio." (PMID 37215572, 2023). "Some lactic acid bacteria strains and their secretory components have anti-proliferation and pro-apoptotic effects on cancer cells by activating pre-caspases, downregulating anti-apoptotic protein Bcl-2, and upregulating pro-apoptotic protein Bax." (PMID 37705007, 2023). "Cancer cells overexpress many proteins that play important roles in resisting activation of the apoptotic cascade, such as Bcl-2, Bcl-xL, and Mcl-1." (PMID 36891274, 2023). "Venetoclax is a BCL-2 inhibitor that has shown efficacy in hematological malignancies in adults and is being investigated in pediatric cancer clinical trials as a promising therapeutic modality." (PMID 37198212, 2023). "By overexpressing anti-apoptotic proteins like Bcl-2 or downregulating pro-apoptotic proteins like Bax through the intrinsic apoptotic pathway, cancer cells can develop apoptotic resistance." (PMID 37591917, 2023). "In this case, Bcl2 expression was found to be present only in small bile ducts and correlated with cancer tissues." (PMID 37509299, 2023). "Bcl-2 up-regulation has been implicate not only in development of many human cancers but also in metastasis and poor prognosis." (PMID 37165800, 2023). "In most cancers, including PC, both proapoptotic proteins are inhibited by high expression of Bcl-2 antiapoptotic proteins, facilitating the evasion of apoptosis." (PMID 36679328, 2023).